PIKFYVE (phosphoinositide kinase, FYVE-type zinc finger containing)
Description:
Dual specificity kinase implicated in myriad essential cellular processes such as maintenance of endomembrane homeostasis, and endocytic-vacuolar pathway, lysosomal trafficking, nuclear transport, stress- or hormone-induced signaling and cell cycle progression. The PI(3,5)P2 regulatory complex regulates both the synthesis and turnover of phosphatidylinositol 3,5-bisphosphate (PtdIns(3,5)P2). Sole enzyme to catalyze the phosphorylation of phosphatidylinositol 3-phosphate on the fifth hydroxyl of the myo-inositol ring, to form (PtdIns(3,5)P2). Also catalyzes the phosphorylation of phosphatidylinositol on the fifth hydroxyl of the myo-inositol ring, to form phosphatidylinositol 5-phosphate (PtdIns(5)P). Has serine-protein kinase activity and is able to autophosphorylate and transphosphorylate. Autophosphorylation inhibits its own phosphatidylinositol 3-phosphate 5-kinase activity, stimulates FIG4 lipid phosphatase activity and down-regulates lipid product formation. Involved in key endosome operations such as fission and fusion in the course of endosomal cargo transport. Required for the maturation of early into late endosomes, phagosomes and lysosomes. Regulates vacuole maturation and nutrient recovery following engulfment of macromolecules, initiates the redistribution of accumulated lysosomal contents back into the endosome network. Critical regulator of the morphology, degradative activity, and protein turnover of the endolysosomal system in macrophages and platelets (By similarity). In neutrophils, critical to perform chemotaxis, generate ROS, and undertake phagosome fusion with lysosomes. Plays a key role in the processing and presentation of antigens by major histocompatibility complex class II (MHC class II) mediated by CTSS. Regulates melanosome biogenesis by controlling the delivery of proteins from the endosomal compartment to the melanosome. Essential for systemic glucose homeostasis, mediates insulin-induced signals for endosome/actin remodeling in the course of GLUT4 translocation/glucose uptake activation (By similarity). Synthesis if (PtdIns(3,5)P2) is required for the cGAS-STING pathway. Supports microtubule-based endosome-to-trans-Golgi network cargo transport, through association with SPAG9 and RABEPK (By similarity). Mediates EGFR trafficking to the nucleus. (Microbial infection) Required for cell entry of coronaviruses SARS-CoV and SARS-CoV-2, as well as human coronavirus EMC (HCoV-EMC) by endocytosis.
Synonyms: KIAA0981; PIP5K3; MGC40423; PIP5K; p235; ZFYVE29; FAB1; HEL37
Tractability: Small molecule: a drug acting on it is in phase 2 or 3 trials; a high-quality ligand is known. Antibody: UniProt places it where antibodies can reach, with high confidence. PROTAC: ubiquitination databases record sites on it; its protein half-life has been measured; a small molecule that binds it is known. Other modalities: a drug acting on it is in phase 2 or 3 trials.
Target class: Enzyme; Transferase
Chemical probes: APY0201, SGC-PIKFYVE-1 (high quality)
Gene: Protein-coding gene on chromosome 2 (208,266,234 to 208,358,755, forward strand). Ensembl gene ENSG00000115020.
Subcellular location: Endosome membrane; Early endosome membrane; Cytoplasmic vesicle, phagosome membrane; Late endosome membrane
Pathways (Reactome):
Metabolism: Synthesis of PIPs at the Golgi membrane; Synthesis of PIPs at the early endosome membrane; Synthesis of PIPs at the late endosome membrane
Gene Ontology:
Molecular function: 1-phosphatidylinositol-3-phosphate 5-kinase activity; 1-phosphatidylinositol-5-kinase activity; protein binding; protein serine kinase activity; 1-phosphatidylinositol-4-phosphate 5-kinase activity; cholesterol binding; phosphatidylinositol-3,5-bisphosphate 5-phosphatase activity; phosphatidylinositol-3,5-bisphosphate binding; protein serine/threonine kinase activity; ATP binding; metal ion binding; phosphatidylinositol kinase activity
Biological process: 1-phosphatidyl-1D-myo-inositol 3,5-bisphosphate metabolic process; antigen processing and presentation of exogenous peptide antigen via MHC class II; melanosome organization; neutrophil chemotaxis; phagosome maturation; phagosome-lysosome fusion; positive regulation of cGAS/STING signaling pathway; protein localization to nucleus; receptor-mediated endocytosis; receptor-mediated endocytosis of virus by host cell; regulation of autophagosome assembly; regulation of reactive oxygen species biosynthetic process; retrograde transport, endosome to Golgi; peptidyl-serine autophosphorylation; phosphatidylinositol 5-phosphate metabolic process; phosphatidylinositol biosynthetic process; protein targeting to membrane; intracellular signal transduction; phosphatidylinositol metabolic process; phosphatidylinositol-3-phosphate biosynthetic process
Cellular component: early endosome membrane; endosome membrane; late endosome membrane; membrane raft; PAS complex; phagocytic vesicle membrane; cytoplasmic vesicle; Golgi membrane; vesicle membrane; cytosol
Genetic constraint (gnomAD): Loss-of-function variants: 114 observed, 254.48 expected, observed/expected ratio (o/e) 0.45, 90% interval 0.38 to 0.52. The upper end of that interval is the gene's LOEUF score, 0.52, which puts it in group 2 of 6, group 1 being the genes least tolerant of losing a copy. Missense variants: 2,123 observed, 2,621.8 expected, observed/expected ratio (o/e) 0.81, 90% interval 0.78 to 0.84. Synonymous variants: 874 observed, 905.22 expected, observed/expected ratio (o/e) 0.97, 90% interval 0.91 to 1.02.
Homologues: Orthologues: chimpanzee PIKFYVE (99% identical), macaque PIKFYVE (99% identical), dog PIKFYVE (95% identical), pig PIKFYVE (95% identical), rabbit PIKFYVE (94% identical), rat Pikfyve (93% identical), guinea pig PIKFYVE (91% identical), mouse Pikfyve (91% identical), tropical clawed frog pikfyve (79% identical), zebrafish pikfyve (71% identical), Drosophila melanogaster fab1 (30% identical), Caenorhabditis elegans ppk-3 (25% identical). Paralogues in human: CCT3 (7% identical), CCT2 (7% identical), CCT6A (6% identical), CCT6B (6% identical), TCP1 (6% identical), CCT7 (6% identical), CCT8 (6% identical), CCT5 (6% identical), CCT4 (6% identical), MKKS (5% identical), CCT8L2 (5% identical), BBS12 (5% identical), and 1 more.
Diseases named in the same sentence as PIKFYVE in open-access papers:
PIKFYVE is named in the same sentence as 82 diseases in open-access papers, as found by Europe PMC text mining. Sharing a sentence is not in itself a finding about the gene and the disease. The quoted sentences say what the papers report.
amyotrophic lateral sclerosis (8 papers, 2016 to 2025). Amyotrophic lateral sclerosis (ALS) is a neurodegenerative disease characterized by progressive muscular paralysis reflecting degeneration of motor neurons in the primary motor cortex, corticospinal tracts, brainstem and spinal cord. "Inhibition of PIKFYVE, an endosomal kinase, was shown to reduce excitotoxicity and restore lysosomal maturation, in a cell model of Amyotrophic Lateral Sclerosis." (PMID 37234859, 2023). "Furthermore, as with TRPML1, mutations in the human PIKfyve complex, namely the FIG4 and Vac14 components, lead to neurodegeneration – in this case, including amyotrophic lateral sclerosis (ALS), Charcot–Marie–Tooth disease, and Yunis–Varon syndrome." (PMID 36825945, 2023). "Clinical trials of published PIKFYVE inhibitors are underway in the treatment of SARS-CoV-2 and other RNA virus infections, as well as amyotrophic lateral sclerosis (ALS) and other neurological diseases." (PMID 38994949, 2024).
corneal dystrophy (7 papers, 2009 to 2024). The term corneal dystrophy embraces a heterogeneous group of bilateral genetically determined non-inflammatory corneal diseases that are usually restricted to the cornea. "Although PIKFYVE is associated with corneal dystrophy, disruption of PIKFYVE has recently been reported to cause pediatric cataracts in humans and zebrafish." (PMID 37511188, 2023).
COVID-19 (7 papers, 2020 to 2024). A disease caused by infection with severe acute respiratory syndrome coronavirus 2. "As PIKfyve inhibition is now being clinically evaluated for efficacy against COVID-19,59,101 our results substantiate the broad potential of PIKfyve inhibition as a DC-enhancing strategy across disease states." (PMID 38464258, 2024). "Here we show that, while Apilimod and other PIKfyve inhibitors have potent antiviral activity in various cell lines against multiple human coronaviruses, these compounds worsen disease in a COVID-19 murine model when given prophylactically or therapeutically." (PMID 35962188, 2022). "Apilimod, the PIKfyve inhibitor used in these studies, has recently been proposed as a drug to investigate further for the treatment of COVID-19, and also blocks the infection of Ebola virus in cells." (PMID 35040777, 2022). "However, though these and past in vitro results suggest that PIKfyve inhibitors have potential value as COVID-19 treatments, this work highlights that in vitro efficacy does not always translate to compound efficacy in vivo." (PMID 35962188, 2022). "The PIKfyve inhibitor apilimod is currently undergoing clinical trials for treatment of COVID-19." (PMID 33375410, 2020). "This may explain our finding that apilimod, but not siPIKfyve, increased viral RNA replication and why apilimod and two other PIKfyve inhibitors could not clear the virus or protect mice from SARS-CoV-2 infection." (PMID 38659941, 2024). "Though these results showed a worsening of disease, the observed immune modulatory effects of PIKfyve inhibitor treatment raised the possibility that a post-exposure treatment regimen could mitigate some of the effects of a cytokine storm, which has been correlated with COVID-19 disease severity." (PMID 35962188, 2022). "Exemplifying this, amongst the most promising targets for early severe COVID-19 predicted by our model were Camostat and Apilimod, primarily targeting TMPRSS2 and PIKfyve respectively." (PMID 35165389, 2022). "Furthermore, the PIKfyve inhibitor Apilimod has been used in several phase I clinical trials for the treatment of Crohn's disease, non-Hodgkin lymphoma, and more recently in the prevention of COVID-19 (clinicaltrials.com, alternative names: STA-5326 and LAM-002)." (PMID 33831417, 2021). "This is the first published work to demonstrate that PIKfyve inhibitors are not protective in a mouse model of COVID-19 and led to increased disease." (PMID 35962188, 2022). "Though these data suggest PIKfyve inhibitors may not be viable COVID-19 therapeutic, Apilimod remains a strong therapeutic candidate for other diseases, including positive human results against cancers and neurodegenerative disorders." (PMID 35962188, 2022).
fleck corneal dystrophy (7 papers, 2008 to 2024). Fleck corneal dystrophy (FCD) is a rare generally asymptomatic form of stromal corneal dystrophy characterized by multiple asymptomatic, non-progressive opacities disseminated throughout the corneal stroma with no effect on visual acuity. "Mutations in PIKFYVE are associated with Fleck Corneal Dystrophy (FCD) (MIM: #121850) with autosomal dominant inheritance." (PMID 37895187, 2023). "In summary, we show here that a novel mutation (p.Glu1389AspfsX16) causing the truncation of the PIKFYVE protein causes fleck corneal dystrophy in the Japanese population." (PMID 23288988, 2012). "The purpose of this study is to report a novel mutation of the PIKFYVE gene in a Japanese patient with fleck corneal dystrophy." (PMID 23288988, 2012). "PIKfyve is a large protein involved in endosome processing, HIV and Salmonella replication, and type 2 diabetes, while mutations in its coding gene are connected to corneal fleck dystrophy (CFD)." (PMID 31035587, 2019). "The phosphoinositide kinase, FYVE finger containing (PIKFYVE) gene has been identified as a gene responsible for fleck corneal dystrophy (FCD)." (PMID 23288988, 2012).
lymphoma (7 papers, 2020 to 2025). A malignant (clonal) proliferation of B- lymphocytes or T- lymphocytes which involves the lymph nodes, bone marrow and/or extranodal sites. "Moreover, PIKfyve inhibition in lymphoma and neuronal cells also causes lysosome swelling and dysfunction leading to autophagosome accumulation, consistent with a role for PIKfyve in maintaining the supply of lysosomes needed for autophagosome fusion to form autolysosomes." (PMID 35968799, 2022). "The discovery that PIKfyve inhibition potentiates OBI cytotoxicity highlights its potential as a co‐therapeutic target for lymphoma treatment." (PMID 40342289, 2025). "Earlier research indicated that the inhibition of PIKfyve can reduce the proliferation and migration of liver cancer cells, lymphoma cells, and fibroblasts, increasing the secretion of exosomes and inducing secretory autophagy." (PMID 39682506, 2024). "The next strongest RPMI-sensitive hits were deguelin, a reported PI3K inhibitor shown to impair cell growth across several cancer types, and apilimod, a putative phosphatidylinositol 3-phosphate 5-kinase (PIKFYVE) inhibitor that has been tested in lymphoma patients." (PMID 39365851, 2024). "However, whether a tubulin inhibitor can be combined with a PIKfyve inhibitor for more aggressive lymphomas has not been explored." (PMID 35091546, 2022).
melanoma (7 papers, 2017 to 2024). A malignant, usually aggressive tumor composed of atypical, neoplastic melanocytes. "PIKFYVE inhibitors selectively kill melanoma cells by disrupting lysosome homeostasis, which triggers an ER‐stress response that upregulates expression of glycosylated interleukin‐24 (IL24)." (PMID 38414326, 2024). "PIKFYVE inhibitor WX8 in sensitive melanoma cells and tumors induces the PERK-dependent ER-stress response with concomitant upregulation IL24 expression." (PMID 38994949, 2024). "The fact that pre‐exposure of autophagy‐dependent melanoma cells to WX8 suppressed their ability to form tumors in mice revealed a hysteresis in their recovery from PIKFYVE inhibition." (PMID 38414326, 2024). "The average levels of IL24 RNA in patient derived melanomas are significantly greater than in samples of normal skin, suggesting that PIKFYVE inhibitors alone will have therapeutic potential against many autophagy‐dependent melanomas." (PMID 38414326, 2024). "Melanoma A375 cells were cultured for 24 h either with 0.05 μm WX8 to selectively inhibit PIKFYVE, or with 1 μm WX8 to inhibit both PIKFYVE and PIP4K2C, or with the vehicle to provide basal levels of gene expression." (PMID 38414326, 2024). "Inhibition of PIKFYVE activity in autophagy‐dependent melanoma cells and tumors upregulates IL24 expression with concomitant amplification of the PERK‐dependent ER‐stress response." (PMID 38414326, 2024). "PIKFYVE inhibition in sensitive melanoma A375 cells prevented its proliferation whereas, the cell death induction only happened when both PIKFYVE and PIP4K2C were inhibited." (PMID 38994949, 2024). "Selective inhibition of PIKFYVE activity by culturing WX8-sensitive melanoma A375 cells in 0.05 μM WX8 arrested cell proliferation without inducing cell death." (PMID 36803256, 2023). "PIKFYVE inhibitors have therapeutic potential to eliminate PIKFYVE-dependent cancer cells, such as those in some melanoma and colorectal cancers, as well as pluripotent cancer stem cells, such those derived from teratocarcinomas." (PMID 36803256, 2023). "In A375 melanoma cells, the phenotype induced by a small-molecule PIKfyve inhibitor YM201636 was strikingly similar to that induced by SB202190, including the characteristic accumulation of large vesicles." (PMID 32531927, 2020). "Moreover, induction of cell death by a PIKFYVE inhibitor together with ectopic expression of IL24 protein was cumulative, thereby confirming the therapeutic potential of PIKFYVE inhibitors in the treatment of melanoma." (PMID 38414326, 2024). "Thus, melanoma cells that produce high levels of IL24 are most likely to be sensitive to PIKFYVE inhibition." (PMID 38414326, 2024). "Melanoma sensitivity to PIKFYVE inhibitors was related directly to IL24 expression." (PMID 38414326, 2024). "Of the three ER-stress sensors that have been described in mammalian cells (i.e., protein kinase PERK, inositol-requiring enzyme IRE1a, and ATF6 transcription factor), PIKFYVE inhibition in sensitive melanoma cells and tumors triggered the PERK-dependent ER-stress response." (PMID 38994949, 2024). "Thus, unlike thapsigargin and tunicamycin, which induce ER‐stress indiscriminately, PIKFYVE inhibitors selectively terminated PIKFYVE‐sensitive melanoma by inducing IL24‐dependent ER‐stress." (PMID 38414326, 2024). "We hypothesized that changes induced in the endolysosomal compartment of melanoma cells in response to PIKfyve inhibition and pyridinyl imidazole compounds might interfere with mTOR subcellular localization." (PMID 32531927, 2020). "Even though the A375 melanoma cells were grown in full media, the PIKfyve inhibitor, as well as the pyridinyl imidazole compounds SB202190 and SB590885, all seemed to disrupt lysosomal mTOR targeting as the mTOR staining pattern changed from dot-like structures to diffuse cytoplasmic staining." (PMID 32531927, 2020). "Thus, inhibition of PIKFYVE inhibited PIKFYVE‐sensitive melanoma cells from forming a tumor." (PMID 38414326, 2024).